SIRT2 (sirtuin 2)
Diseases named in the same sentence as SIRT2 in open-access papers (continued):
Sharing a sentence is not in itself a finding about the gene and the disease.
infection (continued). "Together, all these results suggest that SIRT2 activity towards H3K18 has a direct protective role against the accumulation of excessive DNA damage and is required to promote infection." (PMID 34929015, 2021). "The infection and fatal groups showed considerable increases in several inflammatory factors (gamma interferon [IFN-γ], interleukin 6 [IL-6], IL-8, SIRT2, CCL3, and CXCL10) compared to the control group." (PMID 33593977, 2021). "Consistent with our results using AGK2, infected cells depleted of SIRT2 or TDP-43 by RNAi display significantly elevated levels of γH2Ax in infected cells, as detected by western blot at 24 hours post infection." (PMID 34929015, 2021). "Thus, although we cannot exclude off-target effects, our data suggest that p300/SIRT2 pathway may contribute to the regulation of G6PD activity during IV infection and suggest G6PD as a potential target to control the redox cell environment in virus-infected cells." (PMID 35071051, 2021). "We also found that this dependency is evolutionarily conserved, as adult flies treated with sirtuin inhibitors show decreased infection, and this is exacerbated in SIRT1 or SIRT2 mutants." (PMID 31289184, 2019). "While no aged WT mice died after infection with this virus dose, 37.5% of aged SIRT2 KO mice succumbed." (PMID 40220296, 2025). "In accordance with the transfection experiments, as well as previous infection experiments, expression of endogenous SIRT2 was higher in HBV-infected cells than in non-infected cells (fourth panel, lane 2 vs. 3)." (PMID 40270769, 2025). "From these observations, we propose a tentative conclusion, though debatable, that of the seven sirtuin proteins, SIRT1, 3, 5, and 7 perform a protective function against infections with MTB whereas, SIRT2, SIRT4 and SIRT6 interfere with macrophage pathways facilitating pathogen survival." (PMID 36993975, 2023). "In the absence of TDP-43 or SIRT2, SIRT2-mediated H3K18 deacetylation did not occur and host DNA damage caused by infection accumulated, thus showing a protective role for TDP-43 against DNA damage." (PMID 37762112, 2023). "Others reported that inhibition of SIRT2 with AGK2 restricted the growth of both dug-sensitive and -resistant strains of MTB and enhanced the efficacy of anti-TB drug Isoniazid in the mouse model of infection." (PMID 36993975, 2023). "As expected from our experimental data, brain SIRT2 levels tended to be higher in cART-untreated individuals with HAD compared to those of seronegative individuals, suggesting increased levels of SIRT2 in uncontrolled infection." (PMID 36719240, 2023). "With the same multiplicity of infection (MOI), lysine fatty acylation levels of IcsB substrate proteins are moderately higher in cells infected with IpaJ deletion S. flexneri, consistent with the idea that SIRT2 is upregulated by IpaJ-induced Golgi stress." (PMID 35918380, 2022). "CREB3 KD cells have increased bacterial load after infection which can be partially rescued by WT but not HY SIRT2, suggesting that regulation of SIRT2 is a key function for CREB3 during Shigella infection." (PMID 35918380, 2022). "In the present study, we confirmed the role of SIRT2 in HBV transcription and infection." (PMID 35663860, 2022). "Similar to HeLa cells wildtype and Sirt2-/- MEFs display no decrease in cell viability at 6 hours post infection." (PMID 34929015, 2021). "A time-dependent reduction in SIRT7 mRNA expression was observed in Raw264.7 cells infected with the Mtb virulent strain H37Rv, while there were no significant changes in SIRT2 mRNA expression before and after infection." (PMID 34925356, 2021). "Interestingly, following infection, TDP-43 binding to SIRT2 is further enriched by approximately 2-fold." (PMID 34929015, 2021). "We monitored DNA damage by measuring the nuclear fluorescence intensity of the DNA damage marker γH2Ax during late infection, in the presence or absence of the SIRT2 inhibitor AGK2." (PMID 34929015, 2021).
infection (continued). "Interestingly, although all three of the identified importins function in the basal nuclear shuttling of SIRT2, only IPO7 appears to function during infection with Listeria monocytogenes." (PMID 32042025, 2020). "We found that ablation of Sirt2 in the myeloid lineage had a transient effect in the outcome of infection, with higher bacterial burdens detected on day 30 post infection in the absence of Sirt2." (PMID 26135889, 2015). "Independently of the organ, the long-term control of M. tuberculosis was not compromised by the absence of myeloid Sirt2, as on day 120 post-infection bacterial burdens were similar in both groups of mice." (PMID 26135889, 2015). "Importantly, the SIRT2 modulator, AGK2, substantially blocked the infection-induced changes." (PMID 39458938, 2024). "However, upon infection, interaction between SIRT2 and TDP-43 increases, partially due to SIRT2 phosphorylation, and SIRT2–TDP-43 complexes are loaded onto their targets TSS, with TDP-43 serving as a scaffold for SIRT2." (PMID 37762112, 2023). "Therefore, we show that during infection, the activity of SIRT2 on H3K18 is key in regulating cellular health, which is exploited by L. monocytogenes to maintain host genome integrity and cell viability thereby promoting infection." (PMID 34929015, 2021). "We found SIRT2 protein levels to increase slightly upon AGK2 treatment in uninfected cells and at late infection time points (i.e., 96 HPI), with no significant change in SIRT2 protein levels at 12, 24, 48, or 72 HPI for AGK2-treated samples relative to DMSO." (PMID 37916830, 2023). "Since G6PD levels were also reduced in mock-infected treated cells (data not shown), our data suggest a direct correlation between SIRT2 and G6PD activity during infection." (PMID 35071051, 2021). "Conversely, genes whose expression remains unaltered by infection showed no change in SIRT2 or H3K18-ac, suggesting that SIRT2-dependent H3 deacetylation is gene loci specific." (PMID 32380645, 2020). "Interestingly, additional inhibition of SIRT2 with AGK2 does not have a cumulative effect on intracellular bacterial numbers, suggesting that R-loops and SIRT2 are regulating infection through the same pathway." (PMID 34929015, 2021). "By comparison ARAP2, a SIRT2 independent gene, does not show TDP-43 recruitment upon infection." (PMID 34929015, 2021). "Since inhibition of SIRT1 or SIRT2 was not sufficient, we also tested the combination of EX527 and AGK2 to determine whether that combination could block infection." (PMID 31289184, 2019). "Here, we show that severe acute respiratory syndrome coronavirus 2 (SARS-CoV-2)-infected aged mice lacking SIRT2, a cytosolic NAD+-dependent deacetylase, develop more severe disease and show increased mortality, while treatment with an NAD+ booster, 78c, protects aged mice from lethal infection." (PMID 40220296, 2025). "The role of SIRT2 in MTB infection remains thus unclear, with additional complexities highlighted by Cardoso and colleagues, who found that SIRT2 deletion in the myeloid lineage transiently increased MTB load in the lungs and liver of conditional mice but did not impact long-term infection." (PMID 38683873, 2024). "In contrast to the previous report where myeloid-specific deletion of Sirt2 failed to display long-lasting changes in TB control, administration of AGK2 significantly diminished the bacterial growth at early time points as well as at chronic late phase of infection." (PMID 32697192, 2020).
neurological disorders (26 papers, 2015 to 2025). "In our study in chronic HIV infection, we identified a strong association between plasma levels of SIRT2 with other prominent biomarkers of neurological disorders, such as BDNF, MAPT, and SNCA (32, –, 34)." (PMID 36719240, 2023). "However, there is still little known about the association between SIRT2 and neurological disorders." (PMID 37684620, 2023). "Consequently, dysregulation of SIRT2 has been associated with a broad spectrum of diseases including metabolic and neurological disorders, cancer, and aging." (PMID 36361680, 2022). "SIRT2 is localized in the cytoplasm of both neurons and oligodendrocytes, and the well-known substrate of SIRT2 is α-tubulin, an important component of microtubule cytoskeleton whose acetylation by SIRT2 is linked to brain aging and neurological disorders such as AD and PD." (PMID 37095366, 2023). "Although previous research has widely reported the deacetylation function of SIRT2 in various tissues, particularly its role in metabolic and neurological diseases, its function in articular cartilage remains underexplored." (PMID 40620356, 2025). "While SIRT2 is widely recognized for its role in promoting the progression of neurological disorders, it also serves to safeguard the brain under specific conditions." (PMID 39338285, 2024). "As a nicotinamide adenine dinucleotide‐dependent deacetylase, SIRT2 is mainly expressed in myelinating glia of the central nervous system (CNS) and plays an important role in neurological diseases." (PMID 35393758, 2022). "Recently, accumulating evidence has revealed a relationship between SIRT2 and nervous system diseases." (PMID 35401208, 2022). "In summary, SIRT2 exerts a detrimental effect on majority of neurological diseases, inhibiting SIRT2 by chemical inhibitors, SIRT2 knockout, or siRNA silencing protects the brain." (PMID 34108853, 2021). "As a type of nicotinamide adenine dinucleotide (NAD+)-dependent deacetylases, sirtuin 2 (SIRT2) is predominantly found in the cytoplasm of cells in the central nervous system (CNS), suggesting its potential role in neurological disorders." (PMID 34108853, 2021). "Though SIRT2 inhibitors are promising in curing neurological diseases, we cannot dismiss the paradoxical role of SIRT2 in neuroinflammation, axonal dysfunction, and autophagy." (PMID 34108853, 2021). "In accordance with the role of SIRT2, many SIRT2 inhibitors have been reported to ameliorate the symptoms from neurological disease." (PMID 34650436, 2021). "This review summarized the complex roles SIRT2 plays in the pathophysiology of diverse neurological disorders, compared and analyzed the discrete roles of SIRT2 in different conditions, and provided possible explanations for its paradoxical functions." (PMID 34108853, 2021). "Sustained inflammation mediated by activated microglia is common to most neurologic disorders, and it has been reported that also SIRT2 overexpression inhibited microglia activation through NF-κB deacetylation." (PMID 33597872, 2020). "SIRT2 is an emerging target for therapy of various neurologic diseases, including neurodegeneration, as well as cardiac and metabolic diseases." (PMID 29423902, 2018). "In conclusion, the connection between SIRT2 and neurological disorders is now well established, and thus, the potential of SIRT2 as a therapeutic target deserves to be studied in greater depth." (PMID 29514133, 2018). "Sirtuin 2 (SIRT2), an NAD+-dependent deacetylase that is present in the central nervous system (CNS) and serves as a lysine deacetylase and defatty-acylase, has been associated with neurological disorders." (PMID 39338285, 2024). "In addition, the exact neuroprotective effect offered by HDAC6 or SIRT2 inhibitors in neurological diseases is still unclear." (PMID 37150812, 2023). "Finally, SIRT2 can be mostly found in the cytoplasm of the central nervous system (CNS) cells, supporting its potential role in neurological disorders." (PMID 36361680, 2022).
neurological disorders (continued). "Moreover, previous studies have indicated that SIRT2 modulates immune balance in nervous system diseases via key molecules in different cellular signaling pathways." (PMID 35813508, 2022). "SIRT2 inhibitors have also showed beneficial effects in neurological diseases." (PMID 34650436, 2021). "First, we introduced the biochemistry and physiology of SIRT2, then described the mechanisms SIRT2 plays in different neurological disorders, analyzed why SIRT2 has paradoxical impacts on similar pathological processes, and discussed the possibility of developing drugs targeting SIRT2." (PMID 34108853, 2021). "In the future, the rapid growth in SIRT2 research may clarify its impacts on neurological disorders and develop therapeutic strategies targeting this protein." (PMID 34108853, 2021). "This section mainly focused on SIRT2 modulators targeting neurological diseases." (PMID 34108853, 2021). "The involvement of SIRT2 in QKI-related neurological diseases is gaining increased attention." (PMID 34943825, 2021). "Acetylation of α-tubulin by SIRT2 is closely related to brain aging and neurological disorders." (PMID 34108853, 2021). "In this review, we highlight the regulation of SIRT1 and SIRT2 in various neurological diseases." (PMID 33597872, 2020). "Moreover, 36 showed neurite outgrowth activity in N2a cells, suggesting the possibility of SIRT2-selective inhibitors as therapeutic agents for neurological disorders." (PMID 28989670, 2017). "Therefore, it is reasonable to assume that SIRT2 plays a vital role in neurological disorders." (PMID 34108853, 2021). "Sirtuin 2 (SIRT2, the only member of sirtuin family that is found in the cytoplasm) is involved in regulating neurological diseases." (PMID 35401208, 2022). "SIRT2 might play a negative role in neurological diseases, and it is a hot spot to search for disease-modifying SIRT2 modulators." (PMID 34108853, 2021).
metabolic disorders (22 papers, 2018 to 2025). "SIRT2 is involved in metabolic regulation, and its dysfunction is associated with metabolic disorders, including obesity and diabetes." (PMID 39338285, 2024). "In summary, these results imply that SIRT2 deficiency aggravated the HFCS-induced metabolic disorder to promote the progression of NAFLD." (PMID 37240315, 2023). "Collectively, these results demonstrated that there is an intensive connection between the serum metabolic disorder and the gut microbiota dysbiosis caused by SIRT2 deficiency, the interplay of which may contribute to NAFLD progression." (PMID 37240315, 2023). "Sirt2 is involved in genome integrity and cell function, including cell proliferation and differentiation, and energy metabolism, and Sirt2 activity has been associated with a variety of metabolic diseases." (PMID 34439446, 2021). "In our study, under the HFCS diet, remarkable positive correlations between the gut microbiota dysbiosis and metabolic disorder were explored in the SIRT2 KO mice, revealing that SIRT2 deficiency may promote NAFLD progression through the collaboration between metabolites and gut microbiota." (PMID 37240315, 2023). "In our study, the SIRT2 KO mice exhibited significantly declined hepatoprotective metabolites (PC, LPC, and epinephrine) and elevated harmful metabolites (l-proline), demonstrating that SIRT2 deficiency may promote NAFLD progression through metabolic disorders." (PMID 37240315, 2023). "NAD-dependent deacetylase Sirt2 is involved in mammalian metabolic activities, matching energy demand with energy production and expenditure, and is relevant to a variety of metabolic diseases." (PMID 39004743, 2024). "Sirt2 is thought to be involved in protecting organisms from metabolic disorders through oxidative stress-dependent mechanisms." (PMID 34439446, 2021). "Therefore, SIRT2 can be involved in metabolic disorder-related inflammation and oxidative stress and participate in the pathological process of metabolic disorder-related diseases, rendering SIRT2 a target for the clinical treatment of diseases." (PMID 36101744, 2022). "Sirt2 may be involved in protecting organisms from metabolic disorders through oxidative stress-dependent mechanisms." (PMID 34439446, 2021). "Therefore, Sirt2 may regulate hepatic glucose metabolism and provide a new target for future clinical treatment of metabolic diseases." (PMID 39004743, 2024). "Therefore, targeting Sirt2 may be a potential therapeutic strategy for the treatment of related metabolic disorders." (PMID 39004743, 2024). "Previous studies have evinced that SIRT2 is significantly correlated with CPT1A expression in metabolic diseases and that the in vitro overexpression of ketohexokinase-C (KHK-C) decreases the level of SIRT2 while promoting CPT1A acetylation." (PMID 40606607, 2025). "Our study revealed that SIRT2 is crucial for the progression of NAFLD, which is related to metabolic disorders and gut microbiota dysbiosis." (PMID 37240315, 2023). "Previous studies have reported the regulation of Lkb1 at protein levels, such as SIRT1 and SIRT2 functioned as the upstream regulators for Lkb1/AMPK signaling and played essential roles in the metabolic diseases." (PMID 35986288, 2022).
bacterial infection (18 papers, 2015 to 2026). "SIRT2 has been reported to be upregulated by several stresses, including Golgi stress caused by bacterial infection and nutrient depletion." (PMID 40331334, 2025). "In this context SIRT2 also functions to promote bacterial infection and likewise its chemical inhibition causes a reduction in bacterial burden." (PMID 34929015, 2021). "Of note, both bacterial infections caused the nuclear accumulation of SIRT2, which normally resides predominantly in the cytoplasm, inducing an altered host cell transcriptome that appears likely to support the growth of the pathogens; AGK2 treatment significantly reversed the changes." (PMID 39458938, 2024). "Moreover, Sirt2 deficiency has been shown to cause an impaired bacterial infection, suggesting to be the result of epigenetic regulation of a subset of host cell genes that are necessary for bacterial infection." (PMID 37915600, 2023). "Bacterial infection can induce the expression of the host protein deacetylase SIRT2 to modulate the host immune responses by deacetylating substrate proteins." (PMID 36812247, 2023). "Among them, SIRT2 resides predominantly in the cytoplasm and is highly expressed during bacterial infection, thereby mediating host immune responses." (PMID 36812247, 2023). "Here the authors revealed a role for the protein deacetylase SIRT2 in Golgi stress, particularly induced by bacterial infection." (PMID 35918380, 2022). "We show that multiple importins interact with and contribute to the basal nuclear shuttling of SIRT2 and that one of these, IPO7 is required for SIRT2 mediated H3K18 deacetylation in response to bacterial infection." (PMID 32042025, 2020). "Although the breadth of SIRT2 function remains to be fully characterized, a growing body of literature suggests its role in bacterial infection." (PMID 30452468, 2018). "In various bacterial infection models, such as Mycobacterium tuberculosis, Salmonella, and Listeria monocytogenes, AGK2 chemical inhibitors have been used to inhibit SIRT2 biological activity to explore the role of SIRT2 in bacterial pathogenic mechanisms." (PMID 40317067, 2025). "Overall, SIRT2 has a subtle impact on host defense responses to bacterial infections." (PMID 28894448, 2017). "SIRT2-mediated H3K18 deacetylation also plays a critical role in bacterial infection." (PMID 28445509, 2017). "Similarly, the reduced expression of ADA and SIRT2, both involved in cellular senescence and inflammation, emphasizes the importance of caspase-4 in maintaining cell death and metabolic homeostasis during bacterial infections." (PMID 40137780, 2025). "The NAD-dependent deacetylase Sirtuin-2 (SIRT2) functions in diverse cellular processes including the cell cycle, metabolism, and has important roles in tumorigenesis and bacterial infection." (PMID 32042025, 2020).